VIM (vimentin)
Diseases named in the same sentence as VIM in open-access papers (continued):
Sharing a sentence is not in itself a finding about the gene and the disease.
inflammatory myofibroblastic tumor (4 papers, 2013 to 2024). A multinodular intermediate fibroblastic neoplasm that arises from soft tissue or viscera, in children and young adults. "Among the six types of tissues, I (inflammatory pseudotumor) exhibited an abnormal pattern of immunostaining and was positive for α-SMA, vimentin, as well as TGF-β." (PMID 25189096, 2014). "Myofibroblasts found in inflammatory myofibroblastic tumors, however, stain for alpa-smooth muscle actin, fibronectin, and vimentin, but not for desmin and caldesmon." (PMID 23607022, 2013). "It has been reported that EMA and vimentin staining can help to indicate the origin of the meningeal epithelium of tumors and distinguish LPM from other intracranial lesions, such as IHP, choroid meningioma, inflammatory pseudotumor and sinus histiocytosis with massive lymphadenopathy (SHML)." (PMID 38254159, 2024).
intrahepatic cholangiocarcinoma (4 papers, 2015 to 2021). A carcinoma that arises from the intrahepatic bile duct epithelium in any site of the intrahepatic biliary tree. "Further studies demonstrated that increased abundance of B7-H4 in intrahepatic cholangiocarcinoma up-regulated the mesenchymal marker vimentin and down-regulated the epithelial marker E-cadherin." (PMID 31052260, 2019). "In a previous paper, we reported vimentin expression in intrahepatic cholangiocarcinoma using immunohistochemistry on tissue microarrays (TMA), whereas the 19 HCC included in these TMA were all negative." (PMID 26110787, 2015). "In intrahepatic cholangiocarcinoma (ICC), addition of Ang II resulted in alterations in expression of EMT markers, decrease of CDH1 and increase of vimentin expression level." (PMID 33673178, 2021).
kidney failure (4 papers, 2016 to 2021). An acute or chronic condition that is characterized by the inability of the kidneys to adequately filter the blood. "Pax2 is transiently upregulated six hours post folic acid injection in a model of renal failure in proximal tubular cells along with vimentin expression, a marker of mesenchymal cells." (PMID 26771648, 2016). "Vimentin is a protein whose abundance increases when epithelial-to-mesenchymal transition (EMT) takes place and EMT development can lead to kidney failure." (PMID 33803529, 2021). "Vimentin KO mice do not have a renal phenotype under normal conditions, but with 3⁄4 reduction in renal mass, die of renal failure that appears to be mediated by abnormal vascular tone attributable to increased endothelin-1 expression and sensitivity." (PMID 27942003, 2016). "These differentiated tubular-like cells stably express vimentin, along with E-Cadherin, like immature renal progenitor cells and are able to successfully protect the renal parenchyma against renal failure, whereas more differentiated cells (Vimentin−) are not able to restore renal functionality." (PMID 26771648, 2016).
laryngeal carcinoma (4 papers, 2017 to 2021). Carcinoma that arises from the laryngeal epithelium. "For example, CK2 knockdown also decreases protein levels of slug, snail and vimentin, and increases E-cadherin levels in laryngeal carcinoma cells." (PMID 28134850, 2017). "Our results showed that pepsin exposure reduced the expression of the epithelial marker E-cadherin and increased the expression of the mesenchymal markers vimentin and β-catenin, which was similar to the results observed with immunohistochemistry of laryngeal cancer tissue." (PMID 30936780, 2019). "The increase in vimentin protein expression improved cellular flexibility, mobility, and anti-immune capability, which induced EMT in laryngeal carcinoma." (PMID 30936780, 2019). "Accordingly, western blot assay suggested that the expression of DKK1, vimentin and β-catenin was significantly decreased after YAP downregulated treatment, thereby indicating that YAP mediated the EMT programme and the Wnt/β-catenin signalling pathway in carcinoma of the larynx." (PMID 31269911, 2019).
liposarcoma (4 papers, 2017 to 2026). A usually painless malignant tumor that arises from adipose tissue. "Immunohistochemical analysis revealed positive expression of MDM2, a liposarcoma marker, along with Vimentin, ER, PR, and Ki67, while HER-2 and PCK were negative." (PMID 41518587, 2026). "Additionally, the mesenchymal marker Vimentin showed strong positive expression, whereas the epithelial marker PCK was negative, further supporting the molecular characteristics of liposarcoma." (PMID 41518587, 2026).
liver disease (4 papers, 2019 to 2023). "It is also considered that ECM proteins (e.g., collagen-1, α-SMA and vimentin) are only one of many potentially fibrogenic cell populations in hepatic disorder." (PMID 32365537, 2020). "In the immunohistochemicalanalysis, the vimentin, TWIST and ZEB1 expression were significantly higher in theliver tumor than in other liver diseases (p=0.002, p<0.001, p=0.016,respectively)." (PMID 31038558, 2019).
lung disease (4 papers, 2014 to 2022). "In addition, we will also examine the clinically relevant anti-vimentin compounds and antibodies that could potentially interfere with the pathogenic role of Vimentin intermediate filaments in lung disease." (PMID 35573702, 2022). "A plethora of research studies demonstrate the beneficial effects of anti-vimentin strategies in the treatment of models of various lung diseases." (PMID 35573702, 2022). "This review will focus on the role of Vimentin intermediate filaments in the pathogenesis of various lung diseases." (PMID 35573702, 2022). "Overall, these compounds or their derivatives have the potential as anti-vimentin targets for treating various lung diseases." (PMID 35573702, 2022). "Withaferin A and Ajoene are utilized as anti-vimentin strategies to treat in vitro and in vivo models of lung diseases." (PMID 35573702, 2022). "This study is the first to indicate that the release of high levels of citrullinated fragments of vimentin (VICM) to the circulation may be a specific signal for lung disease." (PMID 25044252, 2014). "There are new clinical trials for non-malignant lung diseases using vimentin as a biomarker and/or drug target (NCT03253146, NCT03584802)." (PMID 35573702, 2022). "This review will analyze the role of vimentin beyond just the epithelial to mesenchymal transition (EMT) marker highlighting its role as a regulator of host-pathogen interactions and signaling pathways for the pathophysiology of various lung diseases." (PMID 35573702, 2022). "Although no direct anti-vimentin molecule is approved for the treatment of any lung disease, there are several clinical trials utilizing interventions that decrease the expression of vimentin." (PMID 35573702, 2022). "Thus, NSCLC cells respond to TGFβ-stimulation with upregulation of several cancer type unspecific (VIM, MYLK, MYL9, TPM1) but also more lung disease specific (MYH15) proteins." (PMID 31113982, 2019).
multiple sclerosis (4 papers, 2016 to 2025). A progressive autoimmune disorder affecting the central nervous system resulting in demyelination. "Post-translational modification of vimentin via citrullination has been reported to critically contribute to multiple sclerosis (MS) and AD pathology." (PMID 40243407, 2025). "Reversion to vimentin expression and to an immature phenotype of astrocytes represents a reactive change, which has been observed also in human neuropathologic conditions such as multiple sclerosis and Alzheimer’s disease." (PMID 36038706, 2022).
myxofibrosarcoma (4 papers, 2012 to 2023). A malignant fibroblastic neoplasm arising from the soft tissue. "Pathology revealed a low-grade myxofibrosarcoma with positive vimentin and SMA, partially positive CD-34." (PMID 36091149, 2022). "The histopathological findings of the present case were further consistent with a diagnosis of low-grade myxofibrosarcoma and immunoreactivity to vimentin and CD34, probably reflecting the tumor’s primitive fibroblastic nature." (PMID 23152982, 2012). "In terms of immunohistochemistry, low-grade myxofibrosarcoma was positive for MUC4, BCL-2, CD99, and vimentin." (PMID 37189471, 2023).
neuroendocrine tumor (4 papers, 2012 to 2024). "The diagnosis of a neuroendocrine tumor in this case is based on the immunohistochemical expression of chromogranin A and vimentin." (PMID 22507757, 2012).
pancreatitis (4 papers, 2011 to 2025). Inflammation of the pancreas. "According to our analysis, Vimentin is expressed in a broader range within DAFs of pancreatitis/pre-disease tissues (3–14%, +/−SEM 0.8%, p = −0.4918) compared to CAFs (4–12%, +/−SEM 2.2%) suggesting that Vimentin is more specific for fibroblasts in a reversible activated state before becoming a CAF." (PMID 40523922, 2025). "Finally, induction of pancreatitis promotes EMT and vimentin expression." (PMID 40307206, 2025).
PEComas (4 papers, 2013 to 2024). "The immunoreactivity of HMB45, SMA, Melan-A, Vimentin, and Desmin in PEComas has been extensively discussed, along with the progression of TFE3 staining positivity in PEComas." (PMID 38689335, 2024). "Otherwise, epithelioid angiomyolipoma is a member of perivascular epithelioid cell tumours (PEComas) which commonly label for HMB-45, Vimentin, and smooth muscle markers and are negative for CD34." (PMID 24490095, 2013).
pilocytic astrocytoma (4 papers, 2013 to 2022). Pilocytic astrocytoma is a rare subtype of low-grade glioma of the central nervous system characterized by a well circumscribed, often cystic, brain tumor with a discrete mural nodule and long, hair-like projections that extend from the neoplastic astrocytes. "Although, pilocytic astrocytoma is GFAP positive, it almost never stains for vimentin, which helps to discriminate it from tanycytic ependymoma." (PMID 23476839, 2013). "These tumors are considered to be more aggressive than pilocytic astrocytomas and immunohistochemically label strongly and diffusely for GFAP and vimentin but are negative for the neuronal markers synaptophysin, neurofilament, chromogranin and epithelial membrane antigen." (PMID 38983553, 2022).
rhabdoid tumor (4 papers, 2021 to 2025). An aggressive malignant embryonal neoplasm usually occurring during childhood. "Rhabdoid tumors can also be characterized through immunohistochemistry (IHC), with common markers including vimentin and epithelial markers such as cytokeratin." (PMID 40315807, 2025). "Rhabdoid tumors of different cell lineages are often positive for the mesenchymal markers vimentin and desmin." (PMID 35645230, 2022). "In general, most rhabdoid tumors stain positive for the mesenchymal markers vimentin and/or desmin." (PMID 35645230, 2022). "The LM F2T2↑ rhabdoid tumor showed a massive upregulation of a unique growth factor program with selectively activated Wnt and SHH/ciliogenesis pathways, and an intermediate filament expression switch, with GFAP loss, and peripherin and vimentin massive overexpression." (PMID 33853673, 2021). "Additional diagnostics such as immunohistochemical staining for the presence of cytokeratin, vimentin, desmin, actin, and WT1 allows distinguishing between other rare cancer types such as renal sarcoma, mesoblastic nephroma, clear cell sarcoma, or rhabdoid tumor." (PMID 34322362, 2021).
salivary gland tumors (4 papers, 2015 to 2024). "According to the results in this study, vimentin and calponin appear to be sensitive immunohistochemical markers of myoepithelial cells in salivary gland tumors, as they exhibit a predominantly intense expression." (PMID 33809250, 2021). "The use of this technique to improve understanding of salivary gland tumors was initiated in the 1980s with studies of intermediate keratin filaments, vimentin, and desmin." (PMID 26550506, 2015). "In consideration of the results of the current study, we argue the practical usefulness of EMA and vimentin in this setting, due to consistent immunoreactivity for such markers in many distinct salivary gland tumors and, to a lesser extent, in odontogenic tumors as well." (PMID 32316524, 2020). "Some of the identified peptides were derived from proteins previously suggested as potential biomarkers of salivary gland tumors (ANXA1, BPIFA2, FGB, GAPDH, HSPB1, IGHG1, VIM) or tumors of other tissues or organs (SERPINA1, APOA2, CSTB, GSTP1, S100A8, S100A9, TPI1)." (PMID 39201484, 2024).
SARS-CoV infection (4 papers, 2016 to 2021). "Vimentin is a putative anti-viral drug target for preventing/reducing the susceptibility to SARS-CoV infection." (PMID 26801988, 2016). "Keratins and vimentin are also used as clinical markers for cancer, while vimentin is suggested to participate in SARS-CoV infection." (PMID 34440729, 2021). "For instance, SARS-CoV infection increases the expression of vimentin, and cell surface vimentin cooperates with angiotensin-converting enzyme 2 (ACE2) to construct the receptor for SARS-CoV S protein." (PMID 32717049, 2020).
spindle cell sarcoma (4 papers, 2006 to 2025). A malignant mesenchymal neoplasm composed of spindle-shaped cells. "Spindle cell sarcomas usually show positive immunoreactivity for vimentin, osteopontin, and MDM2." (PMID 25888133, 2015). "Immunohistochemical staining showed positive immunoreactivity for vimentin and negative for desmin, SMA and CD34 antibodies that are useful to distinguish this type of cancer from other spindle cell sarcomas." (PMID 40788189, 2025).
tongue cancer (4 papers, 2013 to 2022). A malignant neoplasm affecting the tongue. "Vimentin has been evaluated as a useful marker for aggressive pathology and poor prognosis in tongue cancers, and its utility can be explored to assess patients who are more likely to fail treatment, despite being early staged." (PMID 35498535, 2022). "DZNep treatment resulted in a pronounced upregulation of E-cadherin protein together with a remarkable decrease of Vimentin in both tongue cancer cells." (PMID 24345883, 2013).
tongue squamous cell carcinoma (4 papers, 2017 to 2024). A squamous cell carcinoma that arises from the tongue. "CAFs and adjacent cancer fibroblasts were isolated from tongue squamous cell carcinoma and adjacent tissues, and both expressed vimentin but not keratin, while CAFs highly expressed α-SMA and FAP." (PMID 38169376, 2024).
vascular tumor (4 papers, 2011 to 2020). "In addition, vimentin is a marker that is non-specifically expressed by all epithelioid vascular tumors." (PMID 24932310, 2014).
adrenocortical tumor (3 papers, 2011 to 2022). "Assessment of the association among Twist1, fibronectin, vimentin and E-cadherin gene expression in adrenocortical tumor samples." (PMID 34669649, 2022). "Briefly, in murine adrenocortical tumor (Y1) and the mouse Leydig tumor (MLTC-1) cells, vimentin regulated the secretion of progesterone." (PMID 26745512, 2016). "On immunohistochemistry, the tumor was strongly positive for vimentin, CD10, focally positive for epithelial membrane antigen, melan-A and negative for TTF-1, S100, inhibin and synaptophysin The positive vimentin and negative inhibin results weighed against the likelihood of an adrenocortical tumor." (PMID 21569512, 2011).
angioleiomyoma (3 papers, 2008 to 2024). A benign, slow-growing neoplasm that arises from the dermis or subcutaneous tissue. "Many dyes and immunohistochemical tests have been used to identify vascular leiomyomas, including desmine, vimentin, Masson's tricomono, actin and myosin." (PMID 18392517, 2008). "Angioleiomyomas classically show positive immunohistochemical markers like actin, SMA, MSA, desmin, vimentin, h-caldesmon, calponin, and negative markers like HMB45, keratin, and S100." (PMID 38618591, 2024).
astrocytic tumor (3 papers, 2017 to 2025). A glial tumor of the brain or spinal cord showing astrocytic differentiation. "All tumors expressed GFAP (glial fibrillary acidic protein) and vimentin, markers for astrocytic tumors." (PMID 27664151, 2017).
autoimmune hepatitis (3 papers, 2021 to 2022). Hepatitis caused by autoantibodies. "FTCD, a liver-specific enzyme integrating Golgi complex with vimentin filament cytoskeleton, is linked to autoimmune hepatitis and glutamate formiminotransferase deficiency." (PMID 34276651, 2021).
biliary atresia (3 papers, 2012 to 2022). A rare, biliary tract disease characterized by progressive obliterative cholangiopathy of the intra- and extrahepatic bile ducts, occurring in the embryonic/ perinatal period, leading to severe and persistent neonatal jaundice and acholic stool. "For example, SPP1, TGFB1, JAG1, STAT1, and VIM were linked to congenital biliary atresia, and were confirmed to be strongly expressed in the endothelial and megakaryocyte." (PMID 34095116, 2021). "In the EMT process biliary atresia besides a decline in the expression of CK-7 and CK-19, obtained also a decrease other markers of epithelial cells (E-cadherin) and an increase in markers of mesenchymal cells such as N-cadherin vimentin, FSP-1, α-SMA, fibronectin." (PMID 36451979, 2022). "In biliary atresia EMT process, in addition to decrease expression of CK-19 and other epithelial cell markers, also found an increasing in the expression of mesenchymal cells (vimentin, FSP-1, α-SMA, collagen type 1, fibronectin)." (PMID 36451979, 2022).
biliary tract cancer (3 papers, 2021 to 2024). "Similarly, knockdown of ELF3 in biliary tract cancer cells resulted in upregulation of mesenchymal markers such as ZEB1/2, VIM and TWIST1 accompanied by the downregulation of KRT19." (PMID 36864480, 2023).
bladder tumors (3 papers, 2017 to 2024). "RT-PCR was used to test the mRNA levels of CLASP2 and EMT-related markers (E-cadherin and Vimentin) in bladder tumor and urines." (PMID 28166762, 2017).
brain cancer (3 papers, 2019 to 2025). A primary or metastatic malignant neoplasm affecting the brain. "One of these vimentin-reactive antibodies, pritumumab, has been used to treat brain cancer patients." (PMID 40051499, 2025). "EMT array results revealed that TrxR inhibition by IQ10 markedly downregulated a large number of EMT-related genes in brain cancer cells, including several master EMT effectors N-cadherin, Snail, Twist, Vimentin and Zeb, which are usually increased during EMT." (PMID 35344158, 2022). "The maturation of NgR is regulated by the interaction of vimentin and NgR, which attenuates the invasive activity of GBM, and might be a potential therapeutic target for brain cancer." (PMID 31649250, 2019).
brain injuries (3 papers, 2011 to 2016). "In AD, vimentin expression that has also been termed damage response mechanism is limited to Astrocytes, Microglia, and Beta Amyloid plaques, and also is not that much as in Ischemic brain Injury." (PMID 27875990, 2016). "Likewise, knocking down VIM expression using antisense complementary DNA for VIM or preventing hypertrophy of astrocytic processes in GFAP-/-VIM-/-double knockout mice can reduce glial scarring and improve neuronal regeneration and recovery after traumatic brain injuries." (PMID 22146123, 2011).
Burkitt lymphoma (3 papers, 2013 to 2025). A rare form of malignant mature B-cell non-Hodgkin lymphoma. "In our case, tumour cells did not express cytokeratin and bcl-2 but were positive for CD20, CD45 and vimentin, which was more in favour of Burkitt lymphoma." (PMID 41018436, 2025). "In line with this, vimentin is expressed in many B cell types except Burkitt lymphoma." (PMID 24205016, 2013).